CD68 (CD68 molecule)
Diseases named in the same sentence as CD68 in open-access papers (continued):
Sharing a sentence is not in itself a finding about the gene and the disease.
glioblastoma (39 papers, 2013 to 2025). The most malignant astrocytic tumor (WHO grade IV). "However, elevated CD68 expression is also linked to more aggressive tumors and a poor prognosis in various tumor types, including glioblastoma, kidney, hepatocellular, lung and other cancers." (PMID 40395327, 2025). "The density of total CD3+ T lymphocytes and/or CD4+ or CD8+ subsets was increased in six of seven (86%) POLE-mutated primary glioblastomas, and that of CD68+ macrophages in three of seven (43%) POLE-mutated primary glioblastomas compared to the mean density in five POLE WT glioblastomas." (PMID 37990341, 2023). "Genomic analysis between sexes revealed that male glioblastoma patients exhibited increased CD68 mRNA expression." (PMID 38665799, 2024). "CD68 positive cells in glioblastoma are significantly higher than those in the general population of all medulloblastomas." (PMID 29584702, 2018). "High number of CD68 positive microglia and macrophages were detected in the tumor zone bordering necrosis in glioblastomas, whereas in areas with high number of viable tumor cells, microglia and macrophages were more randomly dispersed." (PMID 28467778, 2017). "Moreover, depletion of LDHA in glioblastoma cells or treatment with LDHA inhibitor stiripentol reduced pro-tumor CD45highCD11b+CD68+CD206+ macrophages in tumors from CT2A-bearing mice." (PMID 38443336, 2024). "focused on CD68 expression in various types of cancer and reported that high CD68 levels in tumor samples correlated with adverse prognosis in glioblastoma, kidney renal clear cell carcinoma, lower-grade glioma, hepatocellular carcinoma, lung squamous cell carcinoma, thyroid carcinoma, and thymoma." (PMID 37790755, 2023). "Using a mouse model of glioblastoma, massive infiltration of CD68+ macrophages with bubbly cytoplasm and increased expression of phagocytic cell markers (glycogen, glycoproteins, glycolipids, and mucins) were detected in Sparc-null tumors indicating that SPARC promotes phagocytosis of tumor cells." (PMID 34209679, 2021). "In addition, treatment with a CD68 antibody strongly revealed positive immunostaining inside the human glioblastoma U87-MG tumour." (PMID 26853260, 2016). "Since the CD206/CD68 ratio increases in bevacizumab‐treated glioblastomas (“M2‐rich”), one may envision the application of CSF1R inhibitors in GBMs that recur after bevacizumab therapy." (PMID 26666269, 2016). "Furthermore, treatment with a CD68 antibody revealed strong positive immunostaining inside the human glioblastoma U87-MG tumours." (PMID 26853260, 2016). "The immune cell infiltrate of seven primary glioblastomas and two spinal metastases from seven patients with rare POLE variants as determined by multiplexed fluorescence IHC of immune cell markers CD3, CD4, CD8, CD68, and PD-1 was compared to that in POLE WT glioblastomas." (PMID 37990341, 2023). "In glioblastomas this immunopositivity was enhanced, especially in perinecrotic areas (although frankly necrotic areas were systematically avoided), with increased presence of CD68 immunopositive foamy macrophages and large granular cells, indicative of a degenerative nature." (PMID 24376672, 2013). "Markers of innate immunity including CD68, S100A9, HLADR, NLPR3, interleukin (IL) 1β, IL-6, TNFα and NF-κB were significantly increased in human derived glioblastoma samples compared to healthy control brain." (PMID 41034696, 2025). "We showed glioblastoma invasive margins have a different immune profile compared with the core, including reduced TAM motility/activation (Iba1, CD68), increased homeostatic microglia (P2RY12) and reduced CD4+ T and NK cells." (PMID 37324244, 2023). "Programmed death-ligand 1 expression was associated with microglia/macrophage markers (including anti-inflammatory) CD68, CD163, CD32a and triggering receptor expressed on myeloid cells 2, only in the leading edge of glioblastomas (P < 0.01)." (PMID 37324244, 2023).
glioblastoma (continued). "We also observed a robust number of intratumoral microglia highlighted by CD68 and CD163 immunostaining in de novo RRD glioblastomas." (PMID 38079020, 2023). "Complementary to this, we demonstrated here the bilateral ligand and receptor expression on glioblastoma tissue sections using the specific markers of CD105 for MSCs and CD68 for macrophages." (PMID 32545571, 2020). "In another study, SST2A was also not detected in CD68+ macrophages bordering the necrotic area in glioblastoma." (PMID 40508145, 2025). "In addition, according to the Ivy Glioblastoma Atlas Project database, the distribution of MAP2K3 was consistent with the distribution of macrophage markers CD68 and CD276." (PMID 38938778, 2024). "The primary glioblastoma of patient Fam011-III.1/M1 showed an increased immune infiltrate compared to a POLE WT glioblastoma, which was composed mainly of PD-1-positive CD3+ T lymphocytes co-expressing CD4, and CD68+ macrophages." (PMID 37990341, 2023). "Adding OLA-PEG, a novel CXCL-12 inhibitor, to bevacizumab or B-20 (anti-VEGF agent) significantly improved the anti-tumor effect by reducing intratumoral CD68+ TAM accumulation and by increasing the survival of tumor-bearing mice in the orthotopic G12 human glioblastoma model." (PMID 34209679, 2021). "In addition, according to the database of the Ivy Glioblastoma Atlas Project, the distribution of PD-L1 was consistent with the distribution of the myeloid gene markers such as ITGAM, CD14, and CD68." (PMID 30333036, 2018). "Interestingly, epithelioid glioblastoma cells express MHC class II antigen, CD68, and colony-stimulating factor receptor-1 commonly found in microglia/macrophage lineage, and therefore, they may interact with CD4+ and NK cells in the process." (PMID 36703629, 2022). "CD335 was positively associated with PD-L1 at both the leading edge and infiltrating zone of glioblastomas (P < 0.01) but not in the core; CD335 also positively correlated with CD8+ T cells as well as with CD68/CD163/TREM2 TAMs only at the leading edge (P < 0.01)." (PMID 37324244, 2023). "We examined 40 primary brain tumours (30 glioblastomas and 10 oligodendroglial tumours) with our new technique, namely double-labelling immunohistochemistry for MGMT and a "cocktail" of non-tumour antigens (CD34, CD45 and CD68)." (PMID 24252243, 2013).
lymph node metastasis (39 papers, 2015 to 2025). "Especially, a high CD68+ TAMs density had a significant association with lymph node metastasis in TI (OR = 2.10, 95% CI: 1.19–3.71, P=0.01; I2 = 0) or TS (OR = 1.58, 95% CI: 1.00–2.51, P=0.05; I2 = 0)." (PMID 38501293, 2024). "A preliminary study in oral cavity carcinoma reported that lymph node metastasis was associated with high levels of CD68+ macrophages in tumors." (PMID 33211709, 2020). "Studies assessing the intraepithelial and stromal macrophage population in over 200 primary colorectal tumors showed elevated tumoral CD68+ cell infiltration was associated with increased long-term survival and reduced lymph node metastasis." (PMID 28815041, 2017). "The expression levels of CD68 in tumor cells were only associated with lymph node metastasis (P = 0.044), while the expression of CD163 was significantly associated with the recurrence (P = 0.013) and mortality (P = 0.001)." (PMID 26769084, 2016). "Besides, a high CD68+ TAMs density was significantly associated with lymphatic vessel invasion, vascular invasion, and lymph node metastasis (all P<0.05)." (PMID 38501293, 2024). "A high density of CD68+TAMs is associated with lymph node metastasis." (PMID 34994088, 2022). "In addition, we also analyzed the association between TAMs and clinicopathological characteristics in ESCC patients who underwent surgery, which demonstrated that a high density of CD68+ TAMs was significantly associated with lymphatic vessel invasion, vascular invasion, and lymph node metastasis." (PMID 38501293, 2024). "CD68 protein expression was associated with lymph node metastasis (p = 0.048) and TNM stage (p = 0.029), with more lymph node metastasis and higher TNM stage associated with higher CD68 expression." (PMID 36372883, 2022). "Statistical analysis revealed that only CD68 (p = 0.05, FC = 1.56) was marginally relevantly upregulated in tumor tissues of patients suffering from lymph node metastases." (PMID 35406584, 2022). "In the meta-analysis, high stromal CD68+ TAMs density was relevant to lymph node metastasis (WMD = 11.89, 95% CI: 5.30–18.47)." (PMID 33928349, 2021). "The counts of total CD68+ macrophages were significantly increased in cases presenting with lymph node metastasis (P=0.03)." (PMID 33928349, 2021). "The data revealed that high density of CD68-TAMs was significantly related to ominous clinicopathological characteristics such as lymph node metastasis, high Ki67, poor histological grade, and hormonal receptor negativity (p < 0.001 for all comparisons)." (PMID 34858800, 2021). "Increased CD68+-TAMs were a good prognostic factor of GC in male, tumour diameter ≥ 5 cm, lymph node metastasis and T3 subgroups." (PMID 32765828, 2020). "Our studies demonstrated that in patients with lymph node metastasis the amount of CD68+ macrophages in ductal gaps was lower compared to metastasis-free patients." (PMID 33194645, 2020). "We found there was better prognosis in GC patients with high CD68+-TAMs in males, with GC size ≥ 5 cm, lymph node metastasis and T3 subtypes." (PMID 32765828, 2020). "The lymph node metastasis samples had significantly more CD68 mononuclear positive cells than did the connective tissue of MSR squamous epithelium (p<0.001)." (PMID 31870104, 2019). "There was a greater immunoexpression of inflammatory and CD68 cytokines in primary tumour and lymph node metastasis than in MSR." (PMID 31870104, 2019). "High numbers of CD68+ macrophages infiltrating HNSCC were shown to correlate with lymph node metastasis, extracapsular spread and an advanced stage of disease." (PMID 25949860, 2015). "Furthermore, the infiltration of CD68+ macrophages was significantly correlated with lymph node metastasis." (PMID 39408927, 2024).
lymph node metastasis (continued). "Therefore, by multicolor immunofluorescence and HAO analysis, it was found that with lymph node metastasis of cervical cancer, the number of invasion of CD68 increased significantly, and the spatial distance between CD68 and CD8 decreased significantly." (PMID 37254049, 2023). "The CD68 tumor-associated macrophages in CESC were significantly increased than those in normal tissue or paracarcinoma, and high stromal CD68 tumor-associated macrophages were born on lymph node metastasis." (PMID 36185274, 2022). "Importantly, increased levels of stromal CD68 and CD204 were most significantly associated with lymph node metastasis among the listed clinical parameters." (PMID 35962191, 2022). "Both CD68+ and stromal CD163+ M2 TAM density were associated with lymph node metastasis in CC." (PMID 33928349, 2021). "Moreover, loss of CD47 was associated with increased CD68+ and CD163+ macrophage infiltration, which correlated with reduced tumor grade and lymph node metastasis." (PMID 28815041, 2017). "However, high stromal CD68+ TAMs density was relevant to lymph node metastasis." (PMID 33928349, 2021). "Furthermore, hrHPV+ patients with aggressive tumors, may benefit from such combinatorial therapy, as we showed a probable association between high infiltration rates of CD68+ and CD163+ cells in the peritumoral tumor (PT Tumor) and lymph node metastasis." (PMID 34194435, 2021). "Interestingly, the expression of CD68 in tumor cells was only significantly associated with lymph node metastasis, but not with recurrence and survival." (PMID 26769084, 2016). "We analyzed the correlation between YKL-39, CD68, and CD34 expression and patient gender, age, depth of tumor infiltration, lymph node metastasis, distant metastasis, TNM stage, and degree of differentiation." (PMID 36372883, 2022). "IHC study of 108 samples from patients with EOC demonstrated that CD68+ TAM infiltration and high-mobility group box protein 1 (HMGB1) expression closely correlated with lymph node metastasis and with poor OS." (PMID 33194645, 2020). "Using univariate analysis, it was demonstrated that there is a correlation between survival of GC patients and CD68+ TAMs, tumour diameter, advanced TNM stage and lymph node metastasis in the male GC patients’ subgroup." (PMID 32765828, 2020). "Using univariate analysis a correlation was observed between survival of GC patients and CD68+ TAMs, TNM stage or lymph node metastasis in the T3 stage subgroup of GC patients, respectively." (PMID 32765828, 2020). "We found that CD68 and CD163 double-positive macrophages were more likely to be distributed in tumors with lymph node metastasis (P < 0.001) and had high histological grade (P < 0.001) and Ki67 index (P < 0.001) as well as negative HR expression (P < 0.001)." (PMID 31528210, 2019). "It indicated that the density of CD68+ TAMs in the tumor stroma with lymph node metastasis was higher than that without lymph node metastasis." (PMID 33928349, 2021). "High intraepithelial and stromal expression of CD68 predicted long-term OS and correlated with significantly less tumor budding at the invasive front and absence of lymph node metastasis in the Greek cohort of 201 patients with primary CRC." (PMID 33194645, 2020). "However, low islet CD68+ TAM density was found to be associated with more advanced pathological stage, while high stromal CD68+ TAM density was relevant to male gender, poor differentiation, and the presence of lymph node metastasis." (PMID 27144518, 2016). "Moreover, CD68+/CD206+ M2 macrophage infiltration positively correlated with adverse clinical outcomes, including depth of invasion (p<0.05), lymph node metastasis (p<0.0001), distant metastasis (p<0.05), Gleason patterns (p<0.0001) and advanced TNM stage (p<0.0001)." (PMID 36439868, 2022).
lymph node metastasis (continued). "VEZF1 protein in UBC patients showed a significant positive correlation with SPOP protein expression, and significant negative correlations with the number of CD68+ and CD206+ macrophages or lymph node metastasis (N stage)." (PMID 39479456, 2024). "And the intratumoral density of CD68- and CD163- positive cells in cervical carcinoma with lymph node metastasis was significantly higher than that in non-lymph node metastasis group (both P<0.05)." (PMID 33928349, 2021). "The levels of LMP1, p-ATR, and CD68+/CD206+ in NPC were not correlated with age and sex, but positively correlated with TNM stage and lymph node metastasis rate, which indicated a poor prognosis (*p < 0.05)." (PMID 32917854, 2020). "Our results showed that the expression of p-ATR and CD68+CD206+ in EB virus-positive NPC was not correlated with age and sex, but with TNM stage and lymph node metastasis, suggesting that the high level of p-ATR and M2 is related to the poor prognosis of the patients." (PMID 32917854, 2020).
liver fibrosis (38 papers, 2007 to 2026). "We conclude that HIV/cART-induced liver fibrosis is associated with an accumulation of M2-like (CD68+/MerTK+) macrophages and with activation of IFN-I signaling in the liver of hu-mice." (PMID 35639478, 2022). "HQD exhibited positive protective effects against liver fibrosis; its mechanism of action was associated with protection from hepatocyte apoptosis and the promotion of CD68 expression in the devolopment of liver fibrosis to cirrhosis development." (PMID 22531084, 2012). "Herein, we observed that the densities of peritumoral infiltrated CD163+ cells are positively correlated with expression of CD68+ macrophages, demonstrating that the development of liver fibrosis should be closely linked to the advancement and poor prognosis of HCC." (PMID 36142683, 2022). "Among the various immune cells, CD68 + macrophages interact the most with lymphatic vessels and biliary epithelial cells with periportal IL-17A + cells and M1 macrophages were reported to be associated with postoperative cholangitis and liver fibrosis and clinical outcome." (PMID 39365460, 2024). "Fluorescence co-localization of Nrf1 and CD68+ macrophages was detected in three types of liver fibrosis models." (PMID 41424862, 2026). "Sirius Red staining and CD68 immunofluorescence staining consistently showed that PPARα inhibition reversed the improvement exerted by Fat-1 on liver fibrosis and inflammation." (PMID 40052160, 2025). "A specific increase in the density of CD68+CD11b+ Kupffer cells with liver fibrosis progression was also observed." (PMID 37296834, 2023). "We also used a second mIF panel to better characterize CD11b+ cells in liver fibrosis progression and identified a specific increase in the density of CD68+CD11b+ cells." (PMID 37296834, 2023). "MMT cells were found in specimens from patients with liver fibrosis on the basis of co-expression of macrophage (CD68) and myofibroblast (a-SMA) markers." (PMID 37941043, 2023). "A recent study using mice livers demonstrated an increase in CD68+ macrophages in advanced liver fibrosis or cirrhosis compared to a normal liver." (PMID 36359782, 2022). "Immunohistochemistry detected abundant α-SMA, CD-68, and type I collagen, which are markers of hepatic fibrosis, while functionally, elevated levels of AST, ALT, alkaline phosphatase, and prothrombin were present." (PMID 36411771, 2022). "CD68 as a marker of inflammation and TGFbeta indicating liver fibrosis were comparably induced in the liver of the MCD diet fed mice." (PMID 31521175, 2019). "Ez abolished the enhanced expression of CD11b and CD68 by oxysterols treatment, suggesting a favorable effect of Ez on HF‐induced liver fibrosis as well as steatosis." (PMID 27761360, 2016). "CD68 is a marker of macrophage lineage cells and is expressed in activated Kupffer cells in liver fibrosis." (PMID 26218873, 2015). "The pathophysiological involvement of KCs in DMN-induced liver fibrosis was elucidated by observation of colocalized CD68 and α-SMA using confocal microscopy." (PMID 22531084, 2012). "CD68 expression in the lung increased gradually during the course of DMN-induced liver fibrosis, and PF inhibited CD68 expression in the lung significantly while GdCl3 increased CD68 markedly." (PMID 23237422, 2012). "In fact, the numbers of macrophages significantly increased with progression of liver fibrosis, as evidenced by immunohistochemistry for CD68." (PMID 21731723, 2011). "Notably, MC mice exhibited markedly increased CD68 macrophage infiltration compared to the VC group (P < 0.01), indicative of enhanced monocyte recruitment during hepatic fibrosis." (PMID 41181146, 2025). "Additionally, Fat-1 significantly relieved liver fibrosis and macrophage infiltration in the liver sections, as demonstrated by Picrosirius Red staining and CD68 immunofluorescence staining, respectively." (PMID 40052160, 2025).